IL10 (interleukin 10)
Diseases named in the same sentence as IL10 in open-access papers (continued):
Sharing a sentence is not in itself a finding about the gene and the disease.
infection (continued). "While in the semen, patients infected with ZIKV had higher concentrations of IL-6 and IL-10 than the control, in order to evidence the persistent inflammation since the beginning of the infection." (PMID 31828175, 2019). "In contrast, IFNG produced by bMDM in response to AF2122/97 and G18 infection increased when IL10 was knocked-down." (PMID 31527895, 2019). "At the late phase of infection (72 h post-infection), levels of IL-1Ra, IL-6, IL-8, IL-10, IL-12p40, GM-CSF, TNF-α, MCP-1, and MIP-1b still remained significantly low for ESRD group, as compared to control group." (PMID 31875015, 2019). "Due to the greater transcription of IL10 early in infection, the amount of IL10 protein detected in supernatants was higher in response to infection with AF2122/97 than G18." (PMID 31527895, 2019). "This was significantly different from that presented by the group that was trained from the first week of infection (IE), where the decrease in IL-10 and TGF-β, production and the increase in IFN-γ and IL-12 production occurred concurrently." (PMID 31131262, 2019). "Figures E13B–E13I show negative relationships between neuroendocrine expression and expression of Th1, IL-10, complement, and infection of macrophages and neutrophils." (PMID 30694692, 2019). "Leishmania infantum subverts the host inflammatory response through the adenosine A2A receptor by inducing CD4+FOXP3+ T cells and IL-10 expression impairing the development of Th1-type adaptive immunity and promoting the establishment of infection." (PMID 31608245, 2019). "Neutrophils isolated from both bronchoalveolar lavage fluid and parenchyma of M. tuberculosis infected mice produced IL-10 which downregulated local lung inflammation during chronic phase of infection." (PMID 31849955, 2019). "Resting mφ, CA mφ, or AA mφ were pretreated with IL-10 for 48 h, 24 h before infection with C. trachomatis or simultaneously at time of infection." (PMID 31134002, 2019). "The anti‐inflammatory effects of IL‐10 have been previously associated with viral resolution during CHIKV infection in both patient cohorts and in vivo infections." (PMID 31015278, 2019). "IL-10, an anti-inflammatory cytokine, prevents overly active immune response during infection and also peaks during sleep." (PMID 30918422, 2019). "High levels of IL-10 during the initial phases of infection due to decreased multifunctional CD4 T cells results in higher susceptibility to VL." (PMID 31024534, 2019). "Increased infection rates are further attributed to subdued cytotoxic lymphocyte ratio, inhibited interferon gamma:IL-10 ratio, and heightened levels of plasma IL-10 in alcoholics, suggesting overall suppression of whole blood cell responses." (PMID 35240760, 2019). "The contribution of IL-10 to resolution of infection reflects its tightly controlled expression, which can be a key factor in determining disease outcome (17, –, 19)." (PMID 31776239, 2019). "In contrast, the level of IL-10 and IL-6 in αIFNAR1 treated mice was decreased as compared to Isotype mice at day 21 post-infection." (PMID 31801478, 2019). "In CD8+ T cell-depleted mice, IL-10 production in early stage infection was increased over two-fold relative to infected control animals and IL-10+ CD3− cells were increased, whereas IFN-γ production in the late stage of infection was decreased." (PMID 31608052, 2019). "Among the tested proinflammatory and anti-inflammatory cytokines, there were significant differences in the mRNA expression levels of IL-2, IL-4, IL-6, and IL-10 following infection with the virulent vs. the attenuated strain (p < 0.05)." (PMID 31514454, 2019). "Like natural infection, a gradual surge in the levels of IL-4, IL-10, and TGF-β were observed, while the levels of IFN-γ and TNF-α increased gradually at early infection but were reduced to basal level at chronic infection." (PMID 31031744, 2019).
infection (continued). "In this context, VL patients present a gradual reduction of inflammatory mediator levels (IL-6, IL-8 and IL-10) starting at 30 days after infection." (PMID 30913261, 2019). "A/J C5+/+ mice had higher levels of liver IL-10, IL-1β, IL-12p40, and IL-12p70 and kidney IL-1β, IL-12p40, and IL-12p70 on the sixth day of infection when compared to A/J C5−/− mice." (PMID 31687410, 2019). "This was followed by an 85% reduction in the amount of IL-10 on day 10 of infection (an average of 8 pg/ml in Kcc1M935K compared to 55 pg/ml in WT)." (PMID 31015511, 2019). "More interestingly, the main factor inducing the production of IL-10 by APCs, particularly macrophages, during infection are thought to be nematode cystatins." (PMID 31681308, 2019). "It is remarkable that in other infectious processes, CD4+CD25+ Treg and IL-10 protect against the infection or the disease." (PMID 31481953, 2019). "Further studies showed that immunization with LdCen−/− parasites induces strong pro-inflammatory response including IL-12, IFN-γ, IL-17, and reduced IL-10 production from macrophages compared to virulent wild type L. donovani (LdWT) infection." (PMID 31608064, 2019). "In infection with other Myxozoa, high levels of il-10 were induced by C. shasta, T. bryosalmonae and also in the intestine, but not in head kidney of gilthead sea bream infected E. leei." (PMID 31060624, 2019). "More importantly, in vivo IL-10 neutralization or B cell depletion rendered NOD mice more efficient in clearing the infection suggesting a link between IL-10 secreting B cells and the establishment of chronic infections." (PMID 30881362, 2019). "Our data also showed that IL-10 expression levels in B cells were increased after infection, especially in hepatic B1a cells." (PMID 31194740, 2019). "It is possible that OO induces IL-10+/MHC II+ neutrophils only upon primary infection or during the early stages of a primary infection." (PMID 31889109, 2019). "S. Typhimurium induced the expression of IL-6, IL-8, IL-1β, TNFα and IL-10 genes in CaCo-2 cells after 8-h infection." (PMID 31490973, 2019). "The level of the pro-inflammatory cytokines TNF-α, IL-1β and IL-6 and the anti-inflammatory cytokine IL-10 was quantified at 10 h post-infection in the supernatants of infected MDM." (PMID 31694333, 2019). "Since various cell populations can produce IL-10 during infection and different cell subsets possess IL-10 receptor, it is difficult to characterize the importance of cell-specific IL-10 production by using neutralizing antibodies." (PMID 31803193, 2019). "Most of these genes, including TNFA, IL1B, IFNG, and IL10, were up-regulated during acute phase of infection and their expression gradually declined, following immunological control the infection, at later stages in Mtb-infected rabbits." (PMID 31382404, 2019). "Other conventional pigs infected with Salmonella Typhimurium X4232 showed increased serum levels of IL-8, TNF-α and IL-10 two days post-infection." (PMID 31540295, 2019). "IL-10 production by NK cells in IL-10-GFP mice peaked at day 4 post-infection before declining rapidly by day 6 post-infection." (PMID 31803193, 2019). "Our current treatment module with SSD–CSM-FPEG resulted in a decrease of pro-inflammatory cytokine TNF-α and increase in anti-inflammatory cytokine IL-10, indicating a resolution of inflammation following subsidence of infection." (PMID 31194776, 2019). "On the other hand, and although also considered a susceptible model of VL, C57BL/6 mice never showed this IL-10 upregulation, while the resistant SV/129 mice showed an infection-induced IL-10 upregulation (in CD4+ T cells only) 8 weeks post-infection." (PMID 30881923, 2019). "At the same time, surviving animals had a significantly higher level of IL-10 in the serum at the time of infection." (PMID 31817809, 2019).
infection (continued). "Our investigations on the transcriptional response of bMDM found that the production of TNF and IFNG in response to infection with both M. bovis strains was affected by removing IL10." (PMID 31527895, 2019). "The levels of IL-10, an important anti-inflammatory cytokine, were slightly increased by infection and significantly reduced by ZS2058, but maintained at a comparable level with that in infected mice by LGG." (PMID 30842764, 2019). "Here we found that B1 cells accumulated in the liver after infection and released IL-10 to regulate inflammation." (PMID 31194740, 2019). "The relationship between SNPs in the IL10 gene region and infections with enterovirus has also been examined in several studies." (PMID 31401790, 2019). "Despite the rise in the T-reg cell population, the levels of the major T-reg-dependent cytokine, IL-10, were substantially decreased after day 3 of NTHi infection." (PMID 31548315, 2019). "Results showed that PCV2 infection led to the reduction of CD3−CD19+ B cells in spleens of wild-type mice and il10−/− mice at 14 and 28 d.p.i. compared to mock infection." (PMID 31551984, 2019). "To explore the influence of Rbm47 on IL-10 production in B cells, we attempted to knock down Rbm47 expression in B cells through Rbm47-specific shRNA-expressing lentiviral infection." (PMID 29844590, 2019). "Since IL-6, IL-10, and IL-12 cytokines were considerably elevated in PMNd-Br mice at later stages of acute infection (day 14 of infection; day 9 postdepletion), we explored the effects of anti-Brucella antibodies at these times in PMNd-Br mice." (PMID 30804100, 2019). "Recently study by Rogo and colleagues reported the effects of defined SNPs in IL-1β, IL-10, IL-17, and IL-28 in flu A/H3N2 in Iranian population that showed a higher risk of developing a severe infection." (PMID 31196204, 2019). "Our interest in IL10 arose from the discovery that two strains of M. bovis induced differential expression of IL10 by bMDM, which correlated with the intensity of the bMDM response to infection." (PMID 31527895, 2019). "In a similar chronic model of infection by L. borgpetersenii serogroup Ballum, cytokines IL-1β and IL-10 were upregulated in hamster kidneys compared to OF1 mouse strain after 14 and 21-28 days postinfection." (PMID 31687410, 2019). "IL-10 and IL-4 are important negative regulators of inflammatory responses during the course of infection with T. gondii, which are sufficient to provoke a Th1 immune response to avoid host mortality associated with the development of severe immunopathology." (PMID 31456786, 2019). "Infection of Mz7Mel cells increased the number of Tregs which correlated with a lower level of IL10 in the supernatant." (PMID 31192129, 2019). "On the contrary, increased IL-10 has been reported in the contralateral healthy eye when infection is occurring in the other eye, supporting the idea that IL-10 has an anti-inflammatory function." (PMID 30818819, 2019). "A/J C5+/+ mice had higher levels of liver IL-10, IL-1β, IL-12p40, and IL-12p70 and kidney IL-1β, IL-12p40, and IL-12p70 on the sixth day of infection than A/J C5−/−." (PMID 31687410, 2019). "Further, this IL-10 production suppresses myeloid cell recruitment to sites of infection and correlates with increased host resistance to systemic Lm." (PMID 31552035, 2019). "IL10 was found to regulate a subset of the previously identified transcriptional response of bMDM to infection, but this varied with the two strains of M. bovis investigated." (PMID 31527895, 2019). "N. meningitidis elicits the delayed production of IL-10, with low but detectable levels of this cytokine at 24 h following infection consistent with our previous studies." (PMID 30825881, 2019). "When CD8+ T cells were depleted, the amount of IL-10 produced 7 days after infection and the amount of IL-2 produced 17 days after infection significantly increased relative to the infected control group." (PMID 31608052, 2019).
infection (continued). "On the contrary, CytoD induced a dose-dependent reduction of IL-2 production by DCs, IL-10 by PMNs and IL-1β by MPs in response to infection by all rBCG strains." (PMID 31921172, 2019). "In general, both the pro-inflammatory cytokines (TNF-α and MCP1) and the anti-inflammatory cytokines IL-6 and IL-10 increased 1 hour of infection in the XID infect APerC." (PMID 31536488, 2019). "BG also enhanced the levels of GM-CSF and IL-10 during the early and late stages of infection, respectively, compared to RG." (PMID 31412594, 2019). "During infection with protozoa and bacteria, IL-10 acts as an immune regulator and ameliorates excessive Th1 and CD8+ T cell responses." (PMID 31370350, 2019). "Infection with Schistosoma induces IL-10-producing B cells, a relatively new member in the network of regulatory immune cells." (PMID 31194740, 2019). "In the CD4+ T cell-depleted group, production of IL-2 and IL-10 were decreased in the early stage of infection, and production of IL-17 and TNF-α was decreased in both the early and late stages." (PMID 31608052, 2019). "Using a co-culture model, we found that infection in classically activated macrophages progressed to generate infectious particles in the presence of IL-10-producing C. trachomatis-infected alternatively activated macrophages." (PMID 31134002, 2019). "Infection with this pathogen also significantly reduced fecal levels of IL-10 in untreated control animals." (PMID 31159409, 2019). "While IL10 increased after infection at the last term of gestation, IL4 showed higher levels on the first and second term." (PMID 31533826, 2019). "In particular, first using PRRSV-2 NVSL 97-7895 and then other European strains (2992, 2993), they showed increased IL10 production during infection." (PMID 30862035, 2019). "On the other hand, in PKO mice, IL-10 production by T cells was higher and peaked at day 8 post-infection." (PMID 31803193, 2019). "A significant positive correlation of the IgM gene expression in skin and spleen was found at 1 dpi, while the IL-10 gene expression was negatively correlated at day 8 after infection." (PMID 31220151, 2019). "The data suggests a MAP driven immune response favouring the establishment of infection, as a strong induction of anti-inflammatory mediators such as IL-10, IL-27 and Suppressor of Cytokine Signalling (SOCS) 1 and 3 was observed." (PMID 30733564, 2019). "In contrast, blockade of IFN signaling during persistent LCMV Clone (Cl)-13 infection diminished immunosuppressive signals and decreased levels of IL-10 and PD-L1 expressing immunoregulatory DCs." (PMID 29672594, 2018). "We thus compared the production of IL-1β, IL-17, TNF-α and IL-10 to the number of CFU in the lungs at 96 hours post-infection for each animal." (PMID 29381692, 2018). "Gene expression studies also revealed higher levels of IFNγ as well as IL-10 in the inflamed footpad during enhanced infection." (PMID 29382880, 2018). "In contrast, IL-10 inhibits the effect of pro-inflammatory cytokines which often results in severe disseminated forms of infection." (PMID 30697307, 2018). "The enhancement of MCP-1 aids the recruitment of monocytes at the site of infection and promotes the differentiation of monocytes into macrophages with a M2 phenotype, exhibiting high levels of IL-10 and prostaglandin E2 (PGE2)." (PMID 29755459, 2018). "tbx21 expression was induced upon infection (P<0.0001), as was the expression of il10 (P=0.004), while the expression of the other Th2 markers tested remained relatively constant." (PMID 29590635, 2018). "Indeed, infection caused upregulation of IL-6, TNFα and IL-1β, typically associated with classical activation, as well as of arginase and IL-10, which is linked to regulatory macrophages and may have profound suppressive effects on both innate and adaptive responses." (PMID 29579113, 2018).
infection (continued). "In the present study, we have shown that Tr1 cells expressing CD200R produce IL-10 in L. donovani infection and are significantly reduced in LdCen−/− infection." (PMID 29915577, 2018). "Colon dilation and concomitant inflammation was reduced with IL-10 treatment given at the onset of MHV-68 infection." (PMID 30249047, 2018). "Comparable high bacterial burden were obtained with the widely used K. pneumoniae strain 43816 and IL-10 was produced in similar low amounts 3 days post-infection." (PMID 29381692, 2018). "Transforming growth factor (TGF)-β and interleukin (IL)-10 are important immunosuppressive cytokines potentially related to the immune dysregulation that occurs in the infection of human immunodeficiency virus (HIV)." (PMID 29439673, 2018). "GATA-3+Treg expanding in mLN of infected SPF and GF mice clearly dominated the IL-10-expressing Treg pool in both groups upon infection." (PMID 30349532, 2018). "It has also been reported that signaling induced through TLR2 by M. tuberculosis in macrophages induces the secretion of IL-10, suppresses IL-12, and attenuates the Th1 response, which is critical for controlling infection." (PMID 30581876, 2018). "The decrease in the formation of memory T cells in IFNARfl/fl x Foxp3YFP-Cre mice in Cl-13 infection should be contrasted to the effects of IL-10 producing Treg cells in augmenting memory T cell formation following Armstrong infection." (PMID 29672594, 2018). "In A. phagocytophilum murine infection models, inflammatory hepatic histopathologic injury is abrogated in Ifng−/− and enhanced in Il10−/− animals, confirming an important role for IFNγ in driving tissue injury." (PMID 29686681, 2018). "EV71 infection induces high levels of inflammatory cytokines in host cells such as IL-6, IL-10 and TNF-α, with a cytokine storm recognized as the main cause of severe cardiopulmonary manifestations during this infection." (PMID 30545363, 2018). "During infection with the helminth parasite Nippostrongylus braziliensis, AAMΦ-induced IL-10 and IGF1 suppress the pro-inflammatory Th17 and neutrophil response." (PMID 29352310, 2018). "Since some of the LieIF2 and LieIF2B subunits are able to induce the secretion of IL-10 in B cells from naïve mice, they may be considered virulence factors implicated in the induction of early down-regulatory immune responses that may facilitate the progression of the infection." (PMID 29675401, 2018). "The PD1/PDL1 blockade has been found to restore both CD4+ and CD8+ T cells function, especially in terms of high IFNγ and low IL-10 production, in L. infantum and L. major infections." (PMID 29915577, 2018). "The quantification of cytokines has also demonstrated that DT-treated DEREG mice produce less pulmonary IL-10 than their controls at weeks 6 and 10 post-infection." (PMID 30410119, 2018). "In our study, we only found significant difference of TNF-α response in the 2000 CFU level of infection between the two strains, same as other cytokines including IL-4, IL-10, GM-CSF, IL-1β, IL-2, IL-6, IL-13, and IL-18." (PMID 30577452, 2018). "In agreement with the almost absent nasal shedding, horses infected with Ab4ΔORF1/71 did not develop intranasal IFN-α, IL-10 or sCD14 responses, while Ab4 infected horses secreted IFN-α and IL-10 at the local infection site starting on d2pi and sCD14 on d3pi." (PMID 30440016, 2018). "In MLN, cytokine mRNA levels were mostly unaltered upon infection, with the exception of IL-10 and TNF-α; both cytokines showed significantly elevated expression levels in infected animals (W = 255, P = 0.046 and W = 257, P = 0.040, respectively)." (PMID 29973271, 2018). "Heightened transcription for IL6 and IL10 in MDSCs despite of lower bacterial replication resulted in more abundant cytokine concentrations in supernatants after 24 h of infection." (PMID 30405617, 2018).